DLEU2 (deleted in lymphocytic leukemia 2)
Synonyms: LEU2; TRIM13OS; NCRNA00022; LINC00022; MIR15AHG; ALT1; BCMSUN; DLB2; RFP2; RFP2OS
Gene: Long non-coding RNA gene on chromosome 13 (49,956,669 to 50,126,118, reverse strand). Ensembl gene ENSG00000231607.
Diseases named in the same sentence as DLEU2 in open-access papers:
DLEU2 is named in the same sentence as 57 diseases in open-access papers, as found by Europe PMC text mining. Sharing a sentence is not in itself a finding about the gene and the disease. The quoted sentences say what the papers report.
chronic lymphocytic leukemia (14 papers, 2013 to 2025). "Encoded by the DLEU2 gene, it has been identified as a potential tumor suppressor gene, often deleted in patients with B-cell chronic lymphocytic leukemia." (PMID 40869429, 2025). "For example, DLEU2 (black dotted circle), a potential therapeutic target of chronic lymphocytic leukemia, was expressed in the brain and associated with axon degeneration in the brain." (PMID 31852840, 2019). "DLEU2 is involved in several types of cancer, including chronic lymphocytic leukemia and non-small-cell lung cancer." (PMID 38792557, 2024). "For example, DLEU2 is downregulated in chronic lymphocytic leukemia (CLL), pleomorphic liposarcoma (PL), Pseudoangiomatous Pleomorphic/Spindle Cell Lipoma, pediatric AML, and breast cancer (BC)." (PMID 37095423, 2023). "For example, miR-15a-5p regulates the proliferation and progression of chronic lymphocytic leukemia by suppressing the expression of DLEU2, a host gene of microRNA." (PMID 33618745, 2021). "Deleted in leukemia 1 (DLEU1) and 2 (DLEU2) are two lncRNAs whose genes map in a critical region at chromosome 13q14.3 deleted in more than 50% of chronic lymphocytic leukemia (CLL) patients, and hosting miR-15a and 16–1, a miRNA tumor suppressive cluster." (PMID 29739426, 2018). "A comparable observation to our data has recently been made in chronic lymphatic leukemia, a hematologic cancer that is frequently characterized by focal heterozygous deletion of the DLEU2 (deleted in lymphocytic leukemia 2) gene locus at 13q14." (PMID 29312579, 2017). "Here we describe an example where two lncRNA genes (DLEU1 and DLEU2) are epigenetically deregulated together with a cluster of neighboring protein-coding tumor suppressor genes in almost all patients suffering from chronic lymphocytic leukemia." (PMID 23593011, 2013). "This gene was initially identified as a potential tumor suppressor in B cell chronic lymphocytic leukemia (B-CLL), and in subsequent studies, it was found DLEU2 gene was also significantly downregulated in pediatric acute myeloid leukemia (AML)." (PMID 37095423, 2023). "The two long non-coding RNA (lncRNA) genes DLEU1 and DLEU2 map to a critical region at chromosomal band 13q14.3 that is recurrently deleted in solid tumors and hematopoietic malignancies like chronic lymphocytic leukemia (CLL)." (PMID 23593011, 2013). "Besides, Deleted in Lymphocytic Leukemia 2 (DLEU2) is an RNA gene which is firstly discovered in chromosome 13q14 genomic region, a region that is usually eliminated in B-cell chronic lymphocytic leukemia." (PMID 36229883, 2022). "Moreover, lncRNA DLEU2 was not only involved in NSCLC, but also in clear cell renal cell carcinoma and chronic lymphocytic leukemia, which indicated that lncRNA DLEU2 may act as a biomarker for clinical diagnosis of NSCLC." (PMID 31541993, 2019).
gastric cancer (14 papers, 2018 to 2025). A primary or metastatic malignant neoplasm involving the stomach. "Activation of DLEU2 has been correlated with tumorigenesis of several malignancies, such as gastric cancer and cervical cancer, by regulating the NOTCH signaling pathway." (PMID 35611845, 2022). "The leukaemia 2 gene (DLEU2) has been reported to play an important role in a variety of diseases, especially in tumour diseases, including thyroid cancer, gastric cancer, sarcopenia, and laryngeal squamous cell carcinoma, and has been shown to play a role through the ceRNA mechanism." (PMID 34979896, 2022). "DLEU2 is also significantly overexpressed in gastric cancer and contributes to cell proliferation." (PMID 32591022, 2020). "Additionally, lncRNA DLEU2 was significantly upregulated in gastric cancer and could promote gastric cancer cell proliferation, invasion, and migration." (PMID 37158958, 2023). "miR‐30e also interacts with other lncRNAs to negatively regulate cancer progression such as oncogenic lncRNA DLEU2 that promoted esophageal cancer through the miR‐30e/E2F7 axis and MALAT1 which acted as a molecular sponge of miR‐30e to regulate ATG5 expression and autophagy in gastric cancer." (PMID 35612714, 2022). "However, most reports have shown upregulation of DLEU2 in cancers, including endometrial cancer(EC), renal clear cell carcinoma(ccRCC), esophageal cancer (ESCA), pancreatic cancer (PC), glioma, gastric cancer(GC), non-small cell lung cancer (NSCLC), thyroid cancer(TC), and prostate cancer (PCa)." (PMID 37095423, 2023).
hepatocellular carcinoma (9 papers, 2017 to 2025). A malignant tumor that arises from hepatocytes. "Other studies have shown that DLEU2 has oncogenic roles in non-small cell lung cancer and hepatocellular carcinoma." (PMID 35075115, 2022). "DLEU2 has been shown to play important roles in the progression of multiple cancers, including esophageal cancer, lung cancer, and hepatocellular cancer." (PMID 35075115, 2022). "HOTTIP is upregulated in hepatocellular carcinoma, osteosarcoma, lung, prostate and other cancers; DLEU2 is deleted in lymphocytic leukemia and epigenetically silenced in myeloid leukemia." (PMID 28715488, 2017). "DLEU2 has been shown to be up-regulated in HCC tissue and induce the proliferation in hepatocellular carcinoma cells in a recent study, supporting our findings." (PMID 39397388, 2025). "In addition, DLEU2 promotes cancer cell proliferation by interacting with EZH2 in hepatocellular carcinoma (HCC)." (PMID 37095423, 2023). "Some studies have showed that lncRNA DLEU2 interacted with EZH2 to promote the proliferation, migration and invasion of hepatocellular carcinoma, thus accelerating the malignant progression of hepatocellular carcinoma." (PMID 32587476, 2020). "Deleted in lymphocytic leukemia 2 (DLEU2) was able to directly interact with Hepatitis B protein and enhancer of zeste 2 polycomb repressive complex 2 subunit (EZH2), leading to transcriptional activation of a subset of genes related to hepatocellular carcinoma." (PMID 37036576, 2023). "DLEU2 and SNHG16 expression is upregulated in hepatocellular carcinoma compared with nontumor cirrhotic tissue." (PMID 41465470, 2025).
leukemia (8 papers, 2015 to 2024). A malignant (clonal) hematologic disorder, involving hematopoietic stem cells and characterized by the presence of primitive or atypical myeloid or lymphoid cells in the bone marrow and the blood. "Among these RNAs, the high expression of three risky lncRNAs including AL445228.2, LMO7-AS1 LMO7 antisense RNA, and DLEU2 (deleted in lymphocytic leukemia 2) was associated with shorter overall survival of WT patients." (PMID 36101743, 2022). "DLEU2 is the host gene for miR15a/16–1, it regulates B cell proliferation and has been reported to be deleted or epigenetically suppressed in leukemia." (PMID 38291338, 2024). "DLEU2, a gene located on chromosome 13q14, has frequently been observed to be deleted or epigenetically suppressed in leukaemia and is considered a tumour suppressor." (PMID 33203788, 2020). "In addition, it was found DLEU2, a lncRNA regarded as a tumor suppressor in leukemia, can downregulate miR-30-5p expression in ccRCC cells by acting as a miRNA sponge." (PMID 28569782, 2017).
non-small cell lung carcinoma (8 papers, 2019 to 2024). A group of at least three distinct histological types of lung cancer, including non-small cell squamous cell carcinoma, adenocarcinoma, and large cell carcinoma. "Apart from modulating cell proliferation and invasion, DLEU2 regulates miRNA levels in pancreatic and non-small cell lung cancers." (PMID 37415732, 2023). "Some studies showed that histone deacetylases inhibitor trichostatin A treated non-small cell lung cancer through upregulation of Dleu2/miR-15a/16-140." (PMID 34400675, 2021).
breast cancer (7 papers, 2019 to 2025). A primary or metastatic malignant neoplasm involving the breast. "Existing evidence indicates that lncRNA DLEU2 influences biological processes such as EMT and cancer stem cell (CSC) enrichment in breast cancer through the DLEU2/ROR1 axis." (PMID 40443971, 2025). "Others had not been associated with EOC but had been associated with other cancers, i.e., DLEU2 with endometrial and prostate cancers, LINC00667 with breast cancer, and PRKCQ-AS1 with multiple myeloma." (PMID 37445988, 2023). "DLEU2 was reported to play a role in response to estrogen regulation in human breast cancer cell line." (PMID 32190687, 2020). "In CLL, breast cancer, and lung cancer, DLEU2 downregulates cyclins by upregulating miRNA-15a, leading to cell cycle arrest in the G1 to G0 phase." (PMID 31061821, 2019). "Interestingly, the expressions of THAP9-AS1 and DLEU2 were relatively lower in cluster 3 and were the only five upregulated lncRNAs in breast cancer samples." (PMID 32190687, 2020). "In breast cancer cells, E2F7 competes with E2F1 for binding to the promoter of its target gene, deleted in lymphocytic leukemia 2 (DLEU2)." (PMID 39613162, 2024).
colorectal cancer (6 papers, 2017 to 2022). A primary or metastatic malignant neoplasm that affects the colon or rectum. "In this study, we first identified that the expression of DLEU2 in CRC was positively correlated with colorectal cancer, cell cycle, G1 pathway, and Apical junction signaling sets by GSEA." (PMID 33391439, 2021). "High expression of DLEU2 was positively correlated with colorectal cancer, cell cycle, G1 pathway, and apical junction signaling sets." (PMID 33391439, 2021). "In this signature which consisted of nine prognostic lncRNAs related to redox genes, COLCA1 has been reported and identified as a key lncRNA in colorectal cancer, and DLEU2 has been reported related to the development of multiple cancers." (PMID 33425212, 2020). "The dysregulation of DLEU2 may be associated with the AMPK-FoxO3A axis and thus promote uncontrolled cell growth in colorectal cancer." (PMID 28152521, 2017).
laryngeal carcinoma (6 papers, 2019 to 2022). Carcinoma that arises from the laryngeal epithelium. "LncRNA Dleu2 and miR-16-1 levels were lower in the laryngeal carcinoma tissue compared to adjacent normal tissues." (PMID 31336999, 2019). "DLEU2 was shown to control miR-16-1 to regulate proliferation, invasion and migration in laryngeal cancer." (PMID 31842887, 2019). "DLEU2 exhibits role in the proliferation and survival of laryngeal cancer cells via miR-16-1." (PMID 32591022, 2020). "Therefore, lncRNA Dleu2 and miR-16-1 may serve as potential biomarkers and targets for laryngeal cancer diagnosis and treatment." (PMID 31336999, 2019).
lung carcinoma (6 papers, 2014 to 2025). "Moreover, consistent with recent studies in esophageal cancer and lung cancer, we found that high expression of DLEU2 was related to more advanced T stage and N stage and higher Gleason scores in prostate cancer and that DLEU2 upregulation was associated with poor survival rates." (PMID 35075115, 2022). "siRNA mediated knockdown of HDAC3 reduced cell proliferation with high acetylation of Dleu2/miR-15a/16-1 in the promoter region and up-regulation of miR-15a/16-1 expression in lung cancer." (PMID 25521755, 2014). "DLEU2 knockdown inhibited carcinogenesis and lung cancer invasion via targeting miR-30a-5p." (PMID 36726845, 2023).
osteosarcoma (6 papers, 2017 to 2023). A usually aggressive malignant bone-forming mesenchymal neoplasm, predominantly affecting adolescents and young adults. "In osteosarcoma, DLEU2 acts as a ceRNA to adsorb miR-337-3p, targeting JAK2, and promoting disease progression." (PMID 37095423, 2023). "DLEU2 is upregulated in osteosarcoma and its expression is proportional to tumor size and clinical stage." (PMID 37095423, 2023). "In osteosarcoma and LC, the expression of DLEU2 is contrary, and high expression of DLEU2 inhibits the migration and invasion of tumor cells." (PMID 37095423, 2023). "In addition, DLEU2 expression is different in cervical cancer (CC), osteosarcoma, and colorectal cancer (CRC) in the same cancer." (PMID 37095423, 2023). "MALAT1 and DLEU2 have been shown to promote osteosarcoma progression in previous studies." (PMID 34456631, 2021). "Here, we demonstrated that DLEU2 regulated SGK1 expression by secluding miR-582-5p, which is involved in the pathogenesis of several types of cancer, including bladder cancer, osteosarcoma, and prostate cancer." (PMID 35075115, 2022). "Herein, we screened 6 osteosarcoma-related genes by lncRNA microarray, MALAT1, HCG9, FAM99A, FAM87B, DLEU2, and C8orf49." (PMID 34456631, 2021). "Six genes presented statistically significant expressions (P < 0.05) in osteosarcoma tissues versus paracarcinoma tissues and were screened, which were MALAT1, HCG9, FAM99A, FAM87B, DLEU2, and C8orf49." (PMID 34456631, 2021).
pancreatic cancer (6 papers, 2019 to 2022). "For example, DLEU2 expression is inversely associated with survival among patients with pancreatic cancer, esophageal adenocarcinoma, and clear cell renal cell carcinoma." (PMID 32555190, 2020). "Compared with that in normal tissues, DLEU2 displaysan upregulated expression in pancreatic cancer tissues." (PMID 34552929, 2021). "Silencing of DLEU2 suppresses pancreatic cancer cell proliferation and invasion by upregulating miR-45524." (PMID 31541081, 2019). "In pancreatic cancer, 11 lncRNAs, A2M-AS1, DLEU2, LINC01133, LINC00675, MIR155HG, SLC25A25-AS1, LINC01857, LOC642852 (LINC00205), ITGB2-AS1, TSPOAP1-AS1 and PSMB8-AS1 were identified and validated on a pancreatic ductal adenocarcinoma expression dataset." (PMID 31164492, 2019).
prostate carcinoma (6 papers, 2016 to 2024). A carcinoma that arises from epithelial cells of the prostate gland. "We then investigated the cause of DLEU2 upregulation in advanced prostate cancer." (PMID 35075115, 2022). "The overexpression of E2F2 in prostate cancer cells contributed to upregulation of DLEU2, then facilitated prostate cancer progression, including proliferation, colony formation, migration, and invasion." (PMID 38807594, 2024). "To further explore the pathological roles of DLEU2 in prostate cancer, we first established DLEU2 overexpression and knockdown systems using pcDNA3.1-DLEU2 and sh-DLEU2 in PC-3 and DU145 cells." (PMID 35075115, 2022). "RT-qPCR and western blotting indicated that SGK1 was distinctly upregulated in DLEU2-overexpressing prostate cancer cells and downregulated in DLEU2-knockdown cells." (PMID 35075115, 2022). "Taken together, these results demonstrated that DLEU2 affected prostate cancer progression via the miR-582-5p/SGK1 axis." (PMID 35075115, 2022). "Collectively, our findings provided insights into the oncogenic roles of DLEU2 in prostate cancer progression." (PMID 35075115, 2022). "Our data indicated that overexpression of E2F2 in prostate cancer cells contributed to upregulation of DLEU2, further resulting in aberrant regulation of the miR-582-5p/SGK1 axis." (PMID 35075115, 2022). "In summary, our findings demonstrated that DLEU2 overexpression in advanced prostate cancer tissues was correlated with poor outcomes." (PMID 35075115, 2022). "Taken together, these results revealed that DLEU2 was highly expressed in advanced prostate cancer and was correlated with poor prognosis." (PMID 35075115, 2022). "We demonstrated that high expression of DLEU2 facilitated prostate cancer progression, including proliferation, colony formation, migration, and invasion." (PMID 35075115, 2022). "Accordingly, in this study, we utilized TCGA database and found that the lncRNA DLEU2 exhibited higher expression in advanced prostate cancer, consistent with previous findings in various other types of cancer." (PMID 35075115, 2022). "Consistent with this, we found that DLEU2 was involved in prostate cancer proliferation, migration, and invasion." (PMID 35075115, 2022). "Importantly, DLEU2 knockdown significantly inhibited the growth, proliferation, and colony formation of prostate cancer cells, and these effects were partially rescued by transfection with miR-582-5p inhibitor or SGK1." (PMID 35075115, 2022). "Thus, our results showed that DLEU2 transcription was activated by aberrant E2F2 expression in prostate cancer." (PMID 35075115, 2022). "Patients with prostate cancer displaying high expression of DLEU2 had a poor prognosis." (PMID 35075115, 2022). "Thus, we concluded that DLEU2 contributed to prostate cancer progression via the miR-582-5p/SGK1 axis." (PMID 35075115, 2022). "Moreover, we demonstrated that overexpression of DLEU2 facilitated the proliferation, migration, and invasion of prostate cancer in vitro." (PMID 35075115, 2022). "Furthermore, we found that DLEU2 overexpression promoted the proliferation, migration, and invasion of prostate cancer, whereas DLEU2 knockdown significantly inhibited prostate cancer progression." (PMID 35075115, 2022). "Our results showed that DLEU2 was upregulated in advanced prostate cancer tissues." (PMID 35075115, 2022). "Notably, DLEU2 overexpression strongly promoted the migration and invasion of prostate cancer cells, whereas DLEU2 knockdown significantly inhibited cell migration and invasion." (PMID 35075115, 2022). "Notably, inhibition of miR-582-5p partially rescued the inhibitory effects of DLEU2 on SGK1 expression in prostate cancer." (PMID 35075115, 2022). "However, the functional roles and mechanisms of DLEU2 in prostate cancer progression are largely unknown." (PMID 35075115, 2022). "Finally, we demonstrated that E2F2 contributed to DLEU2 overexpression in prostate cancer." (PMID 35075115, 2022).
prostate carcinoma (continued). "Furthermore, knockdown of DLEU2 attenuated prostate cancer tumorigenesis in vivo." (PMID 35075115, 2022). "Notably, these findings suggested that E2F2-activated DLEU2 may function as a competing endogenous RNA to facilitate prostate cancer progression by targeting the miR-582-5p/SGK1 axis." (PMID 35075115, 2022). "Importantly, DLEU2 was mainly distributed in the cytoplasm of prostate cancer cells." (PMID 35075115, 2022). "To further determine the regulatory mechanism between DLEU2 and SGK1 in prostate cancer, we performed FISH to test subcellular location of DLEU2 in prostate cancer cells." (PMID 35075115, 2022). "In this study, we identified SGK1 as a downstream of DLEU2; the results were confirmed in prostate cancer cells and in TCGA dataset, indicating that SGK1 expression was strongly suppressed by DLEU2 knockdown." (PMID 35075115, 2022). "The most frequently altered lncRNAs were DLEU1 and DLEU2, followed by MEG3 and MT1DP, both of which had the alteration frequency >2% in 313 TCGA prostate cancer patients." (PMID 26590405, 2016). "Mechanistically, DLEU2 promoted serum and glucocorticoid-induced protein kinase 1 (SGK1) expression by acting as an miR-582-5p sponge, and the transcription of DLEU2 was activated by the dysregulation of E2F transcription factor 2 (E2F2) expression in prostate cancer." (PMID 35075115, 2022). "By integrating the expression profiles of lncRNA and mRNA, several screened lncRNAs including DNAJC3-AS1, WDFY3-AS2, LINC00482, and DLEU2 in the subpathways of PI3K-Akt signaling pathway, focal adhesion, and prostate cancer might play crucial roles in orthodontic forces pathogenesis." (PMID 31565070, 2019).
glioma (5 papers, 2021 to 2023). A benign or malignant brain and spinal cord tumor that arises from glial cells (astrocytes, oligodendrocytes, ependymal cells). "In gliomas, DLEU2 regulates PDK3 expression and glioma progression in an miR-186-5p dependent manner." (PMID 37095423, 2023). "In HCC, LSCC, NSCLC, GC, glioma, ESCA and PCa, transwell assay showed that the high expression of DLEU2 promoted the migration and invasion of tumor cells." (PMID 37095423, 2023).